PML (PML nuclear body scaffold)
Diseases named in the same sentence as PML in open-access papers (continued):
Sharing a sentence is not in itself a finding about the gene and the disease.
leukemia (continued). "APL is characterized by a chromosomal translocation, which results in the fusion gene between the genes of promyelocytic leukemia (PML) and retinoic acid receptor α (RAR α), and finally produces a fusion protein, PML-RARα." (PMID 24454695, 2014). "Previous studies showed that As4S4 was able to decrease positive rate of PML-RARα protein in APL patients, and As4S4 also makes redistribution of PML-RARα protein in leukemia cells from APL patients which is quite different from that of RA treatment." (PMID 24454695, 2014). "This is noteworthy because it clearly represented the population that was transformed by PML/RARα to initiate leukemia." (PMID 25568664, 2014). "Mice inoculated with PML/RARα- or DEK/NUP214-positive leukemic cells developed leukemia with a latency of approximately 4 weeks and a penetrance of 100%." (PMID 25568664, 2014). "PML-RAR-α degradation represses the accumulation of PML-RAR-α oncogene products in leukemia cells and subsequently promotes PML-NB formation in APL cells." (PMID 23460888, 2013). "The immediate-early viral protein ICP0, an E3 ubiquitin ligase, is crucial for blocking anti-viral defense mechanisms by degrading promyeloctic leukemia (PML) nuclear bodies (ND10 domains) in the presence of cellular E2-ubiquitin-conjugating enzymes (E2s)." (PMID 23950709, 2013). "Together, these data suggest that OA exerts a cytotoxic effect that inhibits proliferation and induces apoptosis in NB4 cells by targeting PML/RARα, making it a potent therapeutic agent against leukemia." (PMID 24137431, 2013). "In this respect, PML is required for maintenance of the leukemia-initiating stem cell pool in chronic myeloid leukemia." (PMID 23760585, 2013). "Promyelocytic leukemia tumor suppressor gene concentrates in distinct subnuclear structures known as PML-Nuclear Bodies (PML-NB), also called PML Oncogenic Domains (POD), Nuclear Domain 10 (ND10), or Kremer bodies." (PMID 23526763, 2013). "Cytogenetically, APL is marked by a balanced reciprocal translocation between chromosomes 15 and 17, which results in the fusion of the promyelocytic leukemia (PML) and retinoic acid receptor (RAR)α genes." (PMID 24137431, 2013). "Like RNF4, the prototypic cellular STUbL, K-Rta degrades SUMO-2/3 and SUMO-2/3 modified proteins, including promyelocytic leukemia (PML) and K-bZIP." (PMID 23990779, 2013). "A notable exception to this is the use of mitoxantrone monotherapy to treat multiple sclerosis, where secondary leukemia with PML-RARA translocations has been reported as a complication." (PMID 22829791, 2012). "Targeting the fusion protein/co-repressor contact was reported to restore a differentiation response in leukemia cells expressing PML/RARα or AML1/ETO." (PMID 23152790, 2012). "Candidate sites for nuclear virus assembly factories are promyelocytic leukemia nuclear bodies or PML-NBs (previously termed ND10s, PML oncogenic domains, or PODs)." (PMID 22496654, 2012). "TRIM5α was also shown to be crucial for anti-HIV function, and TRIM19/promyelocytic leukemia (PML) has been identified as a cellular factor against viral infection." (PMID 21306652, 2011). "Recent research has shown that the oncogenic effects of PML-RARα fusion protein in leukemia were closely related to the hypermethylation on the promoters of target genes by recruiting DNMT." (PMID 19897545, 2011). "We have previously shown that LMP1 increases the immunofluorescent intensity of promyelocytic leukemia nuclear bodies (PML NBs) through increased expression of PML protein." (PMID 21975125, 2011). "One property of pathogenic ataxin-1 protein is to sequester and disrupt specific nucleoproteins such as promyelocytic leukaemia nuclear domains (PML-NDs)." (PMID 17925862, 2007). "Furthermore, Daxx is a constitutive component of promyelocytic leukemia nuclear bodies (PML NBs), in which it interacts with PML." (PMID 40724953, 2025).
leukemia (continued). "ATO is already used in leukemia to target PML and could be repurposed for fibrosis if carefully dosed, as it might dismantle PML nuclear bodies that propagate TGF-β signaling." (PMID 40149956, 2025). "Since TET1-NBs have never been described, we were intrigued to identify whether these nuclear hotspots interact with the most commonly studied nuclear structures, such as Promyelocytic Leukemia nuclear bodies (PML-NBs) and/or Cajal bodies (CB)." (PMID 38583183, 2024). "Interestingly, this PTEN relocation doesn’t happen in a specific subset of leukemia stem cells because they have a high level of another protein called PML, which prevents HAUSP from affecting PTEN." (PMID 39048945, 2024). "Here, we discover that exposure to irradiation, oxidative or inflammatory stressors induces transient biogenesis of primary cilia, which are then used by stressed cells to communicate with the promyelocytic leukemia nuclear bodies (PML-NBs) to initiate senescence responses in human cells." (PMID 37019904, 2023). "Previous studies have demonstrated that DHX9 is recruited to promyelocytic leukemia nuclear bodies (PML-NBs) in response to IFN-α stimulation and could be involved in the transcriptional regulation of some ISGs attached to PML-NBs." (PMID 36735791, 2023). "Furthermore, PML-NBs, promyelocytic leukaemia nuclear bodies, form structures termed as viral DNA-containing PML-NBs that restrict HSV genetic expression and its subsequent replication." (PMID 36851084, 2023). "Linkage of PML to RARA generates a PML-RARA oncoprotein that acts as a transcription factor that deregulates transcriptional programs blocking the differentiation of hematopoietic progenitor cells and thus causing leukemia." (PMID 36880596, 2023). "An epidemiological study implying a single rate-limiting event in APL based on the constant incidence over life and leukemia development in PML-RARa transgenic mice suggests that the PML-RARa translocation is necessary and sufficient for triggering leukemogenesis." (PMID 37509198, 2023). "Similarly, nucleolar proteins (8.2%, hypergeometric p value = 5.86×e−16) and proteins in promyelocytic leukemia (PML) body (2.0%, hypergeometric p value = 5.79×e−7) are overrepresented in the proteome with 5 or more repeats." (PMID 37332605, 2023). "The PML–RARA fusion oncoprotein induces leukemia by blocking normal myeloid differentiation." (PMID 34193815, 2021). "PML (promyelocytic leukemia) gene was originally identified in acute PML." (PMID 34741430, 2021). "The main protein of PML-bodies is the protein of promyelocytic leukemia (PML)." (PMID 34072343, 2021). "Promyelocytic leukemia (PML) nuclear bodies are condensates of PML proteins." (PMID 33704061, 2021). "Since Mx1 assemblies have often been observed to be distributed in juxtaposition to promyelocytic leukemia (PML) bodies in the nucleus, we tested whether this is also the case for TMxB." (PMID 32907985, 2020). "Previous studies have shown that PML/RARα is necessary but not sufficient to cause leukemia, and cooperating events are required for the development of APL7,8." (PMID 33298855, 2020). "Promyelocytic leukemia (PML) nuclear bodies (NBs) are highly dynamic subnuclear structures." (PMID 32154186, 2020). "In line with increased T-SCE frequency in NONO/SFPQ-depleted cells we observed an increased frequency of co-localization of TRF2 with Promyelocytic Leukemia (PML) nuclear bodies and co-localization of RAD51 with TRF2 in U-2 OS cells that were depleted for SFPQ." (PMID 30824709, 2019).
leukemia (continued). "PML protein and its association with ER-mitochondrial contact sites were important in repressing autophagy, and treatment with As2O3 was shown to reduce the autophagy efficiency by modulating PML protein in NB4 leukemia cells." (PMID 31226817, 2019). "In addition, the mechanisms of ATO cytotoxicity also rely in degradation of the leukemia fusion protein, namely PML-retinoic acid receptor alpha (PML-RARα) restoring PML functions." (PMID 29467594, 2018). "Some therapeutically-targetable leukemia antigens originate from oncogenesis itself and are leukemia cell-specific, such as the BCR/ABL1 fusion protein in CML and Philadelphia (Ph)+ ALL, PML/RAR-α in acute promyelocytic leukemia, FLT3-ITD and mutated NPM1 in AML and IDH1/2." (PMID 29466292, 2018). "Combining the fusion-circRNAs and other products of the PML-RARα fusion gene such as PML(NLS-) might give a better diagnosis efficiency for leukaemia." (PMID 28535767, 2017). "One answer might be the PML-RAT fusion protein in leukemia, which induces DNA hypermethylation and gene silencing at specific target promoters." (PMID 28487473, 2017). "Interestingly, Let-7a is reported to impart chemoresistance in AML cells bearing NPM mutations while increased Let-7c expression can promote granulocyte differentiation of PML/RARα leukemia cells." (PMID 27007052, 2016). "Herpes simplex virus-1 (HSV-1) is the best-studied model in this context, and it was shown that upon nuclear entry HSV-1 genomes are immediately targeted by components of promyelocytic leukemia nuclear bodies (PML-NBs) and the nuclear DNA sensor IFI16 (interferon gamma inducible protein 16)." (PMID 27782081, 2016). "The conventional nested RT-PCR and/or karyotype method detected 240 rearrangements in the 319 patients with leukemia at diagnosis: 61 PML-RARa, 39 RUNX1-RUNX1T1, 32 CBFB-MYH11, 4 MLLT3-MLL, 1 DEK-NUP214, 61 BCR-ABL1, 12 MLL rearranged, 14 TEL-AML1, and 16 TCF3-PBX1." (PMID 25815789, 2015). "Taken together with our previous report that HF blocked NB4 proliferation and reduced the leukemia burden in vivo we postulated that despite the interference of PML/RARα with TFβR1/SARA/SMAD2/3 complex, the TGF-β pathway remain active in APL and contributes for leukemia progression." (PMID 26099922, 2015). "However, recent studies demonstrated that the As2O3 target PML itself plays a critical role in the maintenance of leukemia initiating cells in chronic myeloid leukemia." (PMID 26510911, 2015). "We investigated whether activated STATs may mediate response to ATO treatment not only in PML/RARα but also in DEK/NUP214-positive leukemia." (PMID 25568664, 2014). "First, while the potential therapeutic power of pharmacological inhibitors of FAO may lie in their ability to exhaust stem cells, it remains to be determined whether PML exerts such a role in leukemia stem cells (or LICs)." (PMID 23504288, 2013). "However, the use of PCR in leukemia is limited because only several types of leukemia have specific gene markers such as PML/RARa, AML1/ETO, and bcr/abl." (PMID 23691459, 2012). "Using a separate leukemia dataset we examined the differences in regulatory network structures which best discriminated a set of leukemia samples identified by translocations involving the AML1-ETO fusion gene versus those with translocations involving the PML-RAR fusion gene." (PMID 16670008, 2006). "Further investigation of specific intracellular zinc distribution is warranted, as zinc signaling may play a critical role in leukemia progression by influencing the accumulation of PML‐RARα and BCR‐ABL, as well as modulating processes such as differentiation, apoptosis, and ferroptosis." (PMID 39887881, 2025). "Recent evidence has also hinted that the nucleus may play a role in degradation through the involvement of promyelocytic leukemia-nuclear bodies (PML-NB), comprised of PML and Sp100 proteins, in a process that sumoylates Nrf2 to render it susceptible to SUMO-targeting ubiquitin ligases." (PMID 36497112, 2022).
leukemia (continued). "However, based on murine APL models, it appears that PML/RARα alone is not sufficient to cause leukemia, and cooperating events are required for the development of APL." (PMID 33298855, 2020). "However, leukemia development in transgenic mice expressing PML-RARα occurs after a long latency period, which strongly suggests that PML-RARα collaborates with additional genetic lesions to block differentiation and promote leukemia." (PMID 26545364, 2015). "Therefore, the PML-RARα fusion protein or fusion gene may be selected as a specific leukemia antigen for inducing a specific immune response in patients with APL to further prolong the remission duration and eradicate minimal residual disease." (PMID 23394714, 2013). "In addition, there is mounting evidence that the two major sites of SUMO-1 and SUMO-2/3 accumulation in the cell, the nuclear lamina and promyelocytic leukemia nuclear bodies (PML NBs), may play diverse roles in the DDR." (PMID 23554604, 2013). "Consistent with PML-RARα degradation, ML364 treatment significantly induces apoptosis in APL cell lines and primary leukemia cells." (PMID 41445506, 2025). "The promyelocytic leukemia (PML) promoter, which includes an interferon stimulated response element (ISRE) and an IFN-γ activation site (GAS), enables the direct generation of PML by types I and II IFNs." (PMID 39599888, 2024). "We also found that PD-1H expression was higher in monocytic leukemia cell lines (THP1, U937, MOLM14) than in leukemia cell lines containing RUNX1-RUNX1T1 (Kasumi1) and PML-RARα (HL-60, NB40)." (PMID 38060328, 2024). "In contrast, all-trans retinoic acid (ATRA), which activates RAR signaling and degrades PML-RARA, can effectively drive the myeloid differentiation and inhibit the proliferation of leukemia cells." (PMID 38466568, 2024). "In these previous studies, f-circPR and f-circM9 (from PML-RARα and MLL-AF9, respectively) have been reported to be crucial in promoting leukemia progression and conferring resistance to therapy." (PMID 36613512, 2022). "To address the significance of KLF4 expression in AML, we deleted the KLF4 gene in the MM6 cell line, which represents MLL-rearranged leukemia, and the NB4 cell line which represent PML-RARα PML using CRISPR-Cas9 technology." (PMID 33659038, 2021). "PML plays a key role in the development of leukemia, and recruits proteins for SUMO modification, and we observed that PML promotes the SUMOylation of ERG." (PMID 33842551, 2021). "Primitive CD34+/CD38− HSPCs were suggested to be leukemia-initiating cells for RUNX1-RUNX1T1, PML-RARα, and KMT2A-MLLT3 AML." (PMID 33803739, 2021). "Since the discovery of PML-RARA, more than a dozen diverse translocations involving RARA have been found in rare leukemia patients, often with typical morphological features of APL." (PMID 32295268, 2020). "Among those LAML tumors that have fusions and no driver gene mutations, we identified several well-recognized fusions relevant to leukemia, such as CBFB–MYH11 (number of samples = 3), BCR–ABL1 (n = 2), and PML–RAR (n = 2)." (PMID 29617662, 2018). "Promyelocytic leukemia (PML), also known as TRIM19, MYL, PP8675, or RNF71, is the major component of PML-NBs and plays important roles in genome stability, programmed cell death, and antiviral activities." (PMID 29922292, 2018). "Here, the authors show that mesenchymal stem cells-derived PML is involved in the maintenance of leukemia cells through Cxcl1 and IL6 and that PML inhibition enhances sensitivity to chemotherapy." (PMID 29302031, 2018).
leukemia (continued). "ATRA is thought to act not only by antagonizing PML-RARA-dependent gene regulation, thereby favoring terminal differentiation, but also by degrading the hybrid protein in leukemia initiating cells (LICs)." (PMID 27626703, 2016). "The cells originating from the PML/RARα-, RUNX1/RUNX1T1- or DEK/NUP214-positive LT-HSCs induced leukemia with a high penetrance of 70%, 50% or 80%, respectively." (PMID 25568664, 2014). "We found that the L-IC of PML/RARα-positive leukemia is different from the L-MC, as already described for DEK/NUP214-positive leukemia." (PMID 25568664, 2014). "We found that although acting predominantly as a transcriptional repressor, PML-RARα functionally cooperates with HIF-1α and activates the expression of a number of HIF-target genes, which then regulate leukemia progression at multiple levels." (PMID 24711541, 2014). "Therefore, together with our previous identification of PML as a protective agents against leukemia stem cell exhaustion, these new data reinforce the concept that in specific cell contexts PML may also play oncogenic functions besides its best-known tumor suppressive activities." (PMID 24575390, 2014). "It is well known that abnormal fusion proteins resulting from chromosomal translocations can serve as relative leukemia-specific CTL response targets including the BCR-ABL and PML-RARα fusion proteins." (PMID 23394714, 2013). "With our new knowledge into the underlying mechanism of PML function, the pharmacological targeting of FAO, or the use of PPAR inhibitors in combination with low doses of ATO might exert a synergistic effect on triple-negative breast cancer tumors and possibly other solid tumors or leukemias." (PMID 23936764, 2013). "For some of the genes involved, including MLL, PML, RARA and AML1 (RUNX1) a relatively large number of translocation breakpoints from de novo and therapy related leukemia cases have been determined at the base pair level." (PMID 22829791, 2012). "One of the important arguments used to support a committed progenitor as the leukemic cell of origin has been the successful generation of leukemia using CTSG, Ctsg, and S100A8 loci, which were thought to target PML-RARA to the promyelocyte compartment." (PMID 23056333, 2012). "It has been reported that PML (promyelocytic leukemia protein) plays a role in normal HSCs and BCR-ABL transduced quiescent LSCs, facilitating leukemia initiation and maintenance." (PMID 21297225, 2010). "The high ROS levels generated by the extract did not result in noticeable changes to promyelocytic leukemia nuclear body (PML-NB) formation." (PMID 41154590, 2025). "Our findings imply USP22-dependent surveillance of PML-RARα stability and IFN signaling as important regulator of APL pathogenesis, with implications for viral mimicry, differentiation and cell fate regulation in other leukemia subtypes." (PMID 38467608, 2024). "Conversely, APL with PML::RARA often presents with higher SSC, less expression of CD4, and more frequent overall blood cell reduction, contributing to some extent to the differentiation between the 2 leukemias." (PMID 39432585, 2024). "In a PML-RARa transgenic mice model, low-dose retinoic acid triggers differentiation but does not fully degrade PML-RARa, and thus fails to eradicate leukemia-initiating cells." (PMID 37509198, 2023). "RNase L activation did not lead to apparent changes in either the nuclear lamin network or promyelocytic leukemia (PML) bodies which are nuclear condensates that do not contain RNA (Fig EV2D–G)." (PMID 35355287, 2022). "Therefore, we investigated STAT5 in primary syngeneic AMLs by comparing DEK-CAN-, PML-RARα- and RUNX1-ETO-induced leukemia." (PMID 35941390, 2022).